NOTCH1 (notch receptor 1)
Diseases named in the same sentence as NOTCH1 in open-access papers (continued):
Sharing a sentence is not in itself a finding about the gene and the disease.
sebaceous carcinoma (2 papers, 2021 to 2025). "NOTCH family mutations have been reported in OA metastases and primary extraocular sebaceous carcinomas in one study, and 8/31 (26%) of tumors harbored NOTCH1 mutations in another." (PMID 34445161, 2021). "NOTCH1 alterations were present in 33% of all sebaceous carcinomas in the present study, with indels observed in 2/2 of OA and 1/2 extraocular tumors harboring a mutation." (PMID 34445161, 2021).
skin squamous cell carcinoma (2 papers, 2020). A carcinoma arising from the squamous cells of the epidermis. "We report that CAFs from skin squamous cell carcinomas (SCCs) display chromosomal alterations, with heterogeneous NOTCH1 gene amplification and overexpression that also occur, to a lesser extent, in dermal fibroblasts of apparently unaffected skin." (PMID 33046701, 2020).
status epilepticus (2 papers, 2017 to 2025). Status epilepticus is defined as a continuous seizure lasting more than 30 min, or two or more seizures without full recovery of consciousness between any of them. "On the other hand, Sirtuin3 (Sirt3), a nicotinamide adenine dinucleotide-dependent enzyme, regulates astrocyte activation by attenuating Notch1 signaling, thereby contributing to the inflammatory response following status epilepticus." (PMID 40019515, 2025). "NOTCH1 has been reported to change also in other brain injury models, including pilocarpine and intrahippocampal kainic acid models of status epilepticus (SE)." (PMID 28273100, 2017).
thyroid (2 papers, 2011 to 2018). "Correlation analysis of DEC1 and NOTCH1 expression levels in these lesions showed that these factors were significantly associated in thyroid malignant lesions, and that DEC1 tended to be highly expressed than NOTCH1 in ATC." (PMID 30158530, 2018).
thyroid tumor (2 papers, 2019 to 2023). A benign or malignant neoplasm affecting the thyroid gland. "In thyroid tumors, most studies on the role of Notch1 signaling have mainly investigated MTC because of the association between Notch expression and neuroendocrine development." (PMID 30622441, 2019).
tongue squamous cell carcinoma (2 papers, 2016 to 2024). A squamous cell carcinoma that arises from the tongue. "Here, we present a novel clinical and functional significance of NOTCH1 alterations in early stage tongue squamous cell carcinoma (TSCC)." (PMID 27391340, 2016).
tongue tumor (2 papers, 2015 to 2021). "Activated NOTCH1 demonstrates an anti-proliferative function in tongue tumor cells through the downregulation of Wnt/β-catenin signaling, thereby inducing apoptosis and cell cycle arrest." (PMID 34391381, 2021). "Activated NOTCH1 has an anti-proliferative effect in tongue tumor cells through down-regulation of Wnt/β-catenin signaling, inducing apoptosis and cell cycle arrest." (PMID 26395002, 2015).
Ureteral obstruction (2 papers, 2019 to 2020). Obstruction of the flow of urine through the ureter. "In addition, in kidneys with ureteral obstruction, Notch1 signalling was activated and then induced fibrosis, but this induction was inhibited by the Notch1 inhibitor dibenzazepine (DBZ)." (PMID 31718671, 2019).
urothelial bladder carcinoma (2 papers, 2015 to 2020). "One recent study reported that miR-34a could inhibit cell migration and invasion of invasive urothelial bladder carcinoma through targeting Notch1." (PMID 25878394, 2015).
urothelial carcinoma (2 papers, 2014 to 2025). A malignant neoplasm derived from the transitional epithelium of the urinary tract (urinary bladder, ureter, urethra, or renal pelvis). "Our data indicate that canonical Notch signalling is suppressed in urothelial carcinoma mainly through downregulation of NOTCH1." (PMID 25167871, 2014). "We have investigated the expression of Notch pathway components in urothelial carcinoma tissues and cell lines and the function of NOTCH1 in UC cell lines." (PMID 25167871, 2014). "In normal urothelial cells and urothelial carcinoma cell lines, overexpression of full-length NOTCH1 or its active intracellular domain induced canonical reporters but was not compatible with long-term proliferation of UC cells." (PMID 25167871, 2014). "Collectively, our findings indicate that canonical Notch signalling is lost in urothelial carcinoma mainly via inactivation of NOTCH1, which in normal urothelium may promote specific steps of urothelial differentiation." (PMID 25167871, 2014). "Expression of NOTCH1, DLL1 and JAG1 was further analysed by immunohistochemistry in a set of paraffin-embedded tissues covering urothelial carcinomas of all stages and grades." (PMID 25167871, 2014).
uveal melanoma (2 papers, 2012 to 2025). A melanoma derived from melanocytes of the uveal tract. "Transfection of uveal melanoma cells with a small interfering RNA against Notch1 (siNotch1) effectively suppressed Notch1 expression, resulting in significant cell growth inhibition when combined with H101 treatment." (PMID 22937170, 2012).
vulvar cancer (2 papers, 2020).
acute promyelocytic leukemia (1 paper, 2021). An aggressive form of acute myeloid leukemia (AML), characterized by arrest of leukocyte differentiation at the promyelocyte stage, due to a specific chromosomal translocation t(15;17) in myeloid cells. "TET inhibits human PML-RARα-positive acute promyelocytic leukemia (APL) cell proliferation and induces autophagy by activating ROS generation and Notch1 signaling." (PMID 34575981, 2021).
adrenocortical carcinoma (1 paper, 2024). "JAG1 is the ligand for Notch1, and upregulated JAG1 promotes cell proliferation in adrenocortical carcinoma." (PMID 38474039, 2024).
Aicardi-Goutières syndrome (1 paper, 2024). "NOTCH1-related leukoencephalopathy is a new diagnostic entity linked to heterozygous gain-of-function variants in NOTCH1 that neuroradiologically show some overlap with the inflammatory microangiopathy Aicardi-Goutières syndrome (AGS)." (PMID 38474113, 2024).
alopecia (1 paper, 2022). Hair loss usually from the scalp. "Inactivation of Notch1 in adult mice is characterized by a premature entry into catagen and leads to alopecia." (PMID 35413801, 2022). "NOTCH1 was highly expressed and up-regulated (about fourfold) in giant pandas with alopecia." (PMID 35413801, 2022). "Therefore, alopecia in our giant pandas may be related to dysregulation of Notch signaling and NOTCH1 may be the candidate gene." (PMID 35413801, 2022).
aortic disorder (1 paper, 2024). Pathology involving the thoracic, thoracoabdominal, or abdominal aorta (including aneurysms). "We further identified two common variants (rs3812603 in NOTCH1 intron and—rs73185723 in DVL3) in association with CAVD, which further underlined the importance of this gene in relation to aortic disorders." (PMID 39057646, 2024).
Atrophy (1 paper, 2023). Any weakening or degeneration, especially through lack of use. "Nedd4, another muscle-specific E3-ubiquitin ligase acting through Notch1 signaling, has recently drawn attention because of its implication in denervation-induced muscle atrophy, here unrelated to Notch1 activation." (PMID 37047427, 2023).
autism spectrum disorder (1 paper, 2025). A spectrum of developmental disorders that includes autism, and Asperger syndrome. "NOTCH1, NOTCH2, and ANK2 have also been associated with mental disorders, such as autism spectrum disorder." (PMID 41157308, 2025).
B-cell neoplasm (1 paper, 2019). A group of heterogeneous lymphoid tumors generally expressing one or more B-cell antigens or representing malignant transformations of B-lymphocytes. "Moreover, NOTCH1 promotes the activation of the PI3K-AKT-mTOR and NF-κB signaling pathway, which plays a pivotal role in accelerating cell growth and promoting cell apoptosis not only in T-cell but also in B-cell neoplasms." (PMID 30777096, 2019).
bone cancer (1 paper, 2023). A primary or metastatic malignant neoplasm affecting the bone or articular cartilage. "Lutetium ethylenediaminetetramethylene phosphonate is a radiopharmaceutical commonly used for its analgesic effect in patients with bone cancer, and relaxin inhibits the Notch‐1 pathway in OS cells through the Notch‐1 pathway." (PMID 37441462, 2023).
Cachexia (1 paper, 2023). Severe weight loss, wasting of muscle, loss of appetite, and general debility related to a chronic disease. "To better understand the role of endothelial Notch1 in WAT wasting, we examined whether other key mediators of cachexia are present in NICDiOE-EC WAT, including increased lipolysis, beiging and fibrosis." (PMID 37749321, 2023).
CADASIL (1 paper, 2015). "Mice mutant for Notch1 and Notch3 develop arteriovenous malformations and display hallmarks of the ischemic stroke disease CADASIL." (PMID 26563570, 2015).
carcinosarcoma (1 paper, 2024). A malignant tumor composed of a mixture of carcinomatous and sarcomatous elements. "While the ILC and carcinosarcoma were noted to share mutations in NOTCH1 (c.6685G>A) and TSC1 (c.2647G>A) we were unable to send paired normal samples and it is possible that these VUS could be germline mutations explaining the expression within both tumors." (PMID 39076998, 2024). "Among variants of unknown significance (VUS), two were identified in both carcinosarcoma and ILC samples with approximately 50% VAF, including NOTCH1 (c.6685G>A, p.V229M, VAF 60.6% carcinosarcoma, 48.1% lobular) and TSC1 (c.2647G>A, p.A883T, VAF 58.5% carcinosarcoma, 40.9% lobular)." (PMID 39076998, 2024).
cataract (1 paper, 2025). Partial or complete opacity of the crystalline lens of one or both eyes that decreases visual acuity and eventually results in blindness. "Specifically, we observed significant reductions in JAG1 and Notch receptors (Notch1, Notch2, and Notch3) in the LECs of cataract patients." (PMID 39796164, 2025).
cerebellar tumors (1 paper, 2018). "Although NOTCH1+ and NOTCH1− cells generated similar sizes of primary cerebellar tumors, NOTCH1+ cells produced robust spinal metastases, whereas NOTCH1− cells were unable to produce detectable spinal metastases." (PMID 30297829, 2018). "After establishment of the tumors generated by NOTCH1+ and NOTCH1− cells, the primary recipient cerebellar tumors were harvested and the NOTCH1+ and NOTCH1− cells were resorted from these primary tumors and re-transplanted into the cerebella of secondary recipients (second passage in vivo)." (PMID 30297829, 2018).
cerebrovascular disease (1 paper, 2022). "Taken together, our results suggest that Notch1 signaling is a key regulator under conditions in which mitochondrial function in ECs of the BBB is disrupted and strengthen the effect of Notch1 signaling as a therapeutic target for maintaining BBB integrity in cerebrovascular disease." (PMID 36028880, 2022). "Our findings suggest that Notch1 signaling is a key regulator in ECs of the BBB in the setting of mitochondrial dysfunction and strengthen the effect of Notch1 signaling as a therapeutic target for maintaining BBB integrity in cerebrovascular disease." (PMID 36028880, 2022).
cholestasis (1 paper, 2022). Impairment of the bile flow caused by obstruction within the liver, or outside the liver in the bile duct system. "In response to cholestasis, CCN1 induces the activation of NF-κB through interaction with integrins αvβ3/αvβ5 to induce the expression of Jag1, which in turn activates NOTCH1 to induce cholangiocyte proliferation." (PMID 35708907, 2022).
cholesteatoma (1 paper, 2023). A pathologic process characterized by the proliferation of keratinizing squamous epithelium resulting in the accumulation of keratin and cells in the middle ear and/or mastoid. "Meanwhile, the VAF for NOTCH1 was 2–7%, indicating that somatic mutations accounted for a small portion of cholesteatomas." (PMID 37968650, 2023). "Mutations in cholesteatomas, including NOTCH1 and MYC, were significantly correlated with bone destruction." (PMID 37968650, 2023). "Our findings suggest an association between NOTCH1 and neoplastic features of cholesteatomas." (PMID 37968650, 2023). "Exon sequencing of these genes in 17 cholesteatoma/blood test pairs revealed that somatic variants in MYC and NOTCH1 had the highest frequencies among the examined genes." (PMID 37968650, 2023). "NOTCH1 and MYC mutations correlated significantly with bone destruction (p = 0.0148) but not with granulation tissue formation (p = 0.399) in attic cholesteatomas (n = 14)." (PMID 37968650, 2023). "Therefore, we hypothesized that VAF in NOTCH1 may be useful for identifying the clinical behavior of cholesteatomas, including the degrees of bony destruction." (PMID 37968650, 2023). "Interestingly, recent studies using microarray analysis techniques have demonstrated that cholesteatomas express many tumor-related genes, including proto-oncogenes c-MYC and NOTCH1." (PMID 37968650, 2023).
choroidal neovascularization (1 paper, 2012). An eye disorder described by the growth of new blood vessels that originate from the choroid through a break in the Bruch membrane into the sub–retinal pigment epithelium (sub-RPE) or subretinal space. "Notch 1 and 4 are expressed on retinal endothelial cells during angiogenesis, but also on macrophages that participate in choroidal neovascularization (CNV)." (PMID 22869002, 2012).
clear cell ovarian cancers (1 paper, 2022). "On the other hand, the analysis of benign or borderline ovarian tumors (n = 16) and clear cell ovarian cancers (n = 5) identified low NOTCH1/3 expressions and also presented low expressions of Notch-related lncRNAs and their related gene sets, compared to those in HGSC (n = 79)." (PMID 35326706, 2022).
colorectal mucinous adenocarcinoma (1 paper, 2018). An invasive colorectal adenocarcinoma characterized by the presence of extracellular mucin pools that contain malignant glandular epithelial structures. "Our analysis demonstrates that the expression of Notch-1 is significantly reduced in human colorectal mucinous adenocarcinoma when compared to non-mucinous colorectal adenocarcinoma." (PMID 30323897, 2018). "Our findings emphasize the implication of epithelial Notch-1 in i) controlling intestinal tumorigenesis, and, ii) highlighting a molecular signature in a subset of patients with colorectal mucinous adenocarcinoma that may benefit from targeted screening and subsequent therapeutics." (PMID 30323897, 2018). "Concomitantly, Notch-1 expression is significantly reduced in human colorectal mucinous adenocarcinoma compared to non-mucinous colorectal adenocarcinoma." (PMID 30323897, 2018).
cutaneous T-cell lymphoma (1 paper, 2021). "In cutaneous T-cell lymphoma cell lines gemcitabine treatment induced Notch1 and its target gene expression, and Notch1 knockdown improved gemcitabine anti-proliferative efficiency." (PMID 34680255, 2021).
cystitis (1 paper, 2021). Inflammation of the urinary bladder. "Notch1 signaling contributes to mechanical allodynia associated with CYP-induced cystitis by promoting microglia activation and neuroinflammation." (PMID 34646085, 2021). "After identifying whether Notch1 signaling can modulate mechanical allodynia of cystitis animals, we explored the underlying mechanism of Notch1 signaling promoting mechanical allodynia." (PMID 34646085, 2021). "We were also curious about how Notch1 signaling activated microglia in the SDH of the cystitis model." (PMID 34646085, 2021). "And inhibition of Notch1 signaling by DAPT contributed to the attenuation of mechanical allodynia of the cystitis model." (PMID 34646085, 2021). "More research is needed to explore the specific ligands binding to Notch1 signaling and inducing downstream activities, which contribute to mechanical allodynia in our cystitis model." (PMID 34646085, 2021). "This study is aimed at determining whether and how Notch1 signaling modulates mechanical allodynia of CYP-induced cystitis." (PMID 34646085, 2021). "After validating the upregulation of Notch1 signaling in SDH of cystitis animals, we identified whether inhibition of Notch1 signaling could attenuate mechanical allodynia of CYP-induced cystitis." (PMID 34646085, 2021). "Taken together, Notch1 signaling may promote microglia activation and production of TNF-α and IL-1β, contributing to mechanical allodynia associated with CYP-induced cystitis." (PMID 34646085, 2021). "However, the impact of Notch1 signaling on mechanical allodynia in cyclophosphamide- (CYP-) induced cystitis is unclear." (PMID 34646085, 2021). "Furthermore, treatment with DAPT during or after the cystitis model establishment could inhibit the overexpression of Notch1 signaling." (PMID 34646085, 2021). "Besides, whether and how Notch1 modulates other glial cells and neurons in a cystitis model also need to be addressed." (PMID 34646085, 2021). "However, whether and how Notch1 signaling modulates mechanical allodynia in CYP-induced cystitis is unknown." (PMID 34646085, 2021). "In our present study, we revealed that Notch1 signaling was upregulated in the L6-S1 SDH of the CYP-induced cystitis rat model, and the expression of Notch1 and NICD was negatively correlated with the mechanical withdrawal threshold of the cystitis animals." (PMID 34646085, 2021). "Taken together, our study indicated that Notch1 signaling promoted microglia activation, contributing to mechanical allodynia of CYP-induced cystitis." (PMID 34646085, 2021). "Notch1 and Notch intracellular domain (NICD) were both upregulated in the SDH of the cystitis group." (PMID 34646085, 2021). "This study is aimed at determining the role and mechanism of Notch1 signaling on the initiation and development of mechanical allodynia in a CYP-induced cystitis rat model." (PMID 34646085, 2021). "Furthermore, to confirm the correlation between the Notch1 expression in SDH and the mechanical withdrawal threshold of the cystitis model, we performed a linear regression analysis." (PMID 34646085, 2021). "Moreover, the expression of Notch1 and NICD was negatively correlated with the mechanical withdrawal threshold of the cystitis rats." (PMID 34646085, 2021). "Inhibition of Notch1 signaling with a γ-secretase inhibitor, DAPT, could attenuate mechanical allodynia of cystitis animals by suppressing microglia activation as well as overexpression of TNF-α and IL-1β." (PMID 34646085, 2021). "Moreover, we only used one concentration level of DAPT to inhibit Notch1 signaling, and we need to further investigate the effect of different concentration levels of DAPT on mechanical allodynia of cystitis animals." (PMID 34646085, 2021). "Therefore, we speculated that Notch1 signaling could regulate microglia activation in SDH, contributing to the mechanical allodynia of the CYP-induced cystitis model." (PMID 34646085, 2021).
demyelination (1 paper, 2021). "Importantly, knockdown Notch1 in astrocytes not only decreased inflammatory production both in vivo and in vitro, but also reduced inflammatory cell infiltration and demyelination lesion in the spinal cords of EAE mice." (PMID 33971906, 2021). "Inhibiting the Notch1 pathway in oligodendrocytes improved remyelination in EAE mice and in the cuprizone (CPZ) demyelination model." (PMID 33971906, 2021).